RHOA (ras homolog family member A)
Diseases named in the same sentence as RHOA in open-access papers (continued):
Sharing a sentence is not in itself a finding about the gene and the disease.
anaphylactic shock (3 papers, 2017 to 2020). "Interestingly, interfering with RhoA/Rho‐kinase signalling abolished endothelial permeability and passive cutaneous anaphylaxis by using either endothelial RhoA genetic deletion or Rho‐kinase inhibitor fasudil." (PMID 32355562, 2020). "Moreover, EC-specific KO of RhoA in adult mice partially rescues this change in permeability, and inhibiting ROCK can protect against lethal systemic anaphylaxis." (PMID 31174284, 2019). "Although RhoA and ROCK have been recently recognized as key targets mediating histamine-induced vascular leakage and anaphylactic shock, our results do not reveal significant differences in MLCK/ROCK1 when Rcan1 is overexpressed in HV-ECs." (PMID 29104573, 2017).
astrocytic tumor (3 papers, 2020 to 2021). A glial tumor of the brain or spinal cord showing astrocytic differentiation. "Concordant with the results for RhoB, Khalil and El-Sibai observed low expression of RhoA and RhoB in astrocytic tumors." (PMID 33162807, 2020). "RhoA and RhoB expression was significantly reduced in astrocytic tumors and their levels were inversely proportional to tumor grade, ie, lower expression was associated with a higher grade and therefore a more aggressive neoplasm." (PMID 33327966, 2020).
Ataxia (3 papers, 2012 to 2025). Ataxia refers to impaired coordination of voluntary muscle movement. "Further protein–protein interaction analysis highlighted MAPK1 (Mitogen-Activated Protein Kinase 1) and RhoA (Ras homolog family member A) as the central nodes in a dysregulated signaling cluster linked to cerebellar ataxia." (PMID 41007684, 2025).
autosomal dominant polycystic kidney disease (3 papers, 2020 to 2023). Autosomal dominant form of polycystic kidney disease. "Polycystin-1, the major protein mutated in autosomal dominant polycystic kidney disease, activates centrosomal RhoA activity via interaction with the Rho-GAP protein ARHGAP35, resulting in shorter cilia." (PMID 32663194, 2020). "Downregulation of YAP/TAZ or c-Myc by inhibiting RhoA suppresses cystogenesis in a mouse autosomal dominant polycystic kidney disease model resulting from Pkd1 deficiency, and the G-protein-coupled receptor (GPCR) signaling could act through RhoA to regulate the Hippo-YAP pathway." (PMID 34365464, 2021).
brain cancer (3 papers, 2020). A primary or metastatic malignant neoplasm affecting the brain. "According to the literature, RhoA was published to mediate microtubule-dependent cell polarisation and directed cell migration of human brain cancer cells." (PMID 33318498, 2020). "Moreover, the expression of both RhoA and RhoB was tested in different types of brain cancer cells, and results showed that as the malignancy of the brain tumor increased, the levels of RhoA and RhoB expressions decreased." (PMID 32089990, 2020).
brain tumor (3 papers, 2006 to 2020). "The overexpression of ROCK-1, which is induced by activated RhoA, is related to brain tumor metastasis." (PMID 26715733, 2016).
cervical squamous cell carcinoma (3 papers, 2020 to 2025). A squamous cell carcinoma arising from the cervical epithelium. "RhoA overexpression has been associated with a significantly reduced disease-free and distant metastasis-free survival in cervical squamous cell carcinoma." (PMID 35604542, 2022).
colorectal adenoma (3 papers, 2019 to 2023). An adenoma that arises from the colon or rectum. "A loss of glycogen synthase kinase 3 alpha (GSK3A) and RAS homolog family member A (RHOA) expression in plasma may function as a biomarker of colorectal adenoma, a precancerous lesion of CRC." (PMID 35954375, 2022). "The expression of RHOA in colorectal adenoma was significantly lower than those in normal plasma samples (0.35-fold with adjusted P < 0.05)." (PMID 31506480, 2019). "Using targeted mRNA sequencing, we found that GSK3A and RHOA had significant difference in gene expression in colorectal adenoma patients as compared with normal healthy subjects." (PMID 31506480, 2019). "RHOA was detected in all of normal and colorectal adenoma plasma samples with the median normalized expression of 147689.4 (range: 2341.2–936329.4) and 167443.6 (range: 2409.3–490713.5) CPM in normal and colorectal adenoma, respectively." (PMID 31506480, 2019). "Both GSK3A and RHOA showed a significantly lower expression in plasma samples from colorectal adenoma patients as compared to normal controls." (PMID 31506480, 2019). "Our preliminary results showed that GSK3A and RHOA were downregulated in the plasma of colorectal adenoma patients as compared to those of colonoscopy-proven normal subjects." (PMID 31506480, 2019). "Reduced GSK3A expression may be due to a dysfunctional immune response in colorectal adenoma, and inactivation of RHOA induces cancer cells to invade and de-differentiate through the Wnt signaling pathway." (PMID 37446204, 2023). "Our team also demonstrated that the downregulation of RAS homolog family member A (RHOA) and glycogen synthase kinase 3 alpha (GSK3A) expression in plasma may function as a diagnostic biomarker of colorectal adenoma using a target sequencing approach." (PMID 37446204, 2023). "Glycogen synthase kinase 3 alpha (GSK3A) and ras homolog family member A (RHOA) were two differential expressed genes (DEGs) detected between normal and colorectal adenoma based on the cut-off of fold change >2 and adjusted P value < 0.05." (PMID 31506480, 2019). "Therefore, the AUC values of GSK3A and RHOA showed that the performance of those 2 genes are not good enough for the detection of colorectal adenoma as compared to FIT and faecal DNA test." (PMID 31506480, 2019).
cutaneous T-cell lymphomas (3 papers, 2019 to 2023). "RHOA mutations are also observed in other tumors, such as adult T-cell leukemia, cutaneous T-cell lymphomas, Burkitt lymphoma, and diffuse-type gastric cancer." (PMID 37370838, 2023). "Furthermore, some primary cutaneous T-cell lymphomas harbor RHOA mutations, usually the N117I mutation." (PMID 37370838, 2023).
diabetic cardiomyopathy (3 papers, 2014 to 2023). Diabetic cardiomyopathy is a disorder of the heart muscle in people with diabetes. "Recent studies have revealed the significant role of the RhoA/ROCK signalling pathway in the underlying mechanisms of diabetic cardiomyopathy." (PMID 37217862, 2023). "As the underlying mechanisms have increasingly come to light, the RhoA/ROCK signalling pathway is proposed to contribute to the pathogenesis of diabetic cardiomyopathy." (PMID 37217862, 2023). "The RhoA/ROCK pathway contributes to diabetic cardiomyopathy in part by promoting the sustained activation of PKCβ2 but the details of their interaction are unclear." (PMID 24466133, 2014). "The level of iNOS is associated with the induction of RhoA expression in the hearts of diabetic rats, while CAPA inhibits LPS/IFN-γ-induced iNOS expression, implicating that the inhibition of iNOS expression may contribute to its protection against diabetic cardiomyopathy." (PMID 24923878, 2014). "Although the RhoA/ROCK signalling pathway is of increasing importance in cardiovascular disease therapy, ROCK inhibition is not the classic method for diabetic cardiomyopathy therapy compared with glucose control." (PMID 37217862, 2023).
energy metabolism disorder (3 papers, 2017 to 2021). "In summary, Rb1 was able to target and inactivate RhoA and downstream signaling, which likely mediated the protective role of Rb1 in I/R-induced energy metabolism disorder and cardiomyocyte apoptosis, providing an explanation for the restoration of heart structure and function by Rb1 after I/R." (PMID 28327605, 2017). "Supporting this speculation, the present study demonstrated that Rb1 prevented I/R-enhanced expression of RhoA and activation of its downstream signaling, including ROCK1, MYPT and MLC, concurrently attenuating energy metabolism disorder and myocardium impairment." (PMID 28327605, 2017). "More importantly, our previous study also demonstrated that RhoA/ROCK signaling pathway is one of the modulator of ATP5D expression and ATP production, and that NR1, a major effective ingredient of Panax notoginseng, was able to prevent I/R-induced energy metabolism disorder via inhibiting ROCK14." (PMID 28327605, 2017).
hypertensive nephropathy (3 papers, 2019 to 2022). Kidney damage that results from chronically elevated blood pressure; complications include glomerular damage resulting in proteinuria and hematuria. "According to the results obtained in this work, we postulate that there is a direct correlation between the activity of a RhoA/ROCK-dependent pathway, Cx43 and renal damage in this model of hypertensive nephropathy." (PMID 31500276, 2019).
inflammatory bowel disease (3 papers, 2019 to 2021). A spectrum of small and large bowel inflammatory diseases of unknown etiology. "Interestingly, thiopurines, drugs often used in the treatment of inflammatory bowel disease (IBD), have been shown to prevent activation of Rac1, resulting in a relative shift in the Rac1/RhoA balance towards RhoA." (PMID 33973626, 2021).
intracerebral hemorrhage (3 papers, 2014 to 2023). A cerebrovascular disorder characterized by bleeding into one or both cerebral hemispheres including the basal ganglia and the cerebral cortex. "In turn, this finding is consistent with the report that exogenous FGF treatment dependent on FGFR-induced activation of PI3K-Akt-Rac1 signaling inhibits RhoA activity and protects the blood-brain barrier after intracerebral hemorrhage in mice." (PMID 36969192, 2023). "A recent study reported that intracerebral hemorrhage disrupts the blood–brain barrier (BBB) function via activation of IL-1β/RhoA/ROCK/NFκB signaling, which results from increased degradation of the inhibitor of κB (IκB)." (PMID 35215244, 2022). "The GTPase RhoA is known to play an important role in the regulation of endothelial tight junctions, and inhibition of RhoA by fibroblast growth factor preserves BBB integrity in a mouse model of intracerebral hemorrhage." (PMID 24579051, 2014).
leiomyoma (3 papers, 2013 to 2023). A well-circumscribed benign smooth muscle neoplasm characterized by the presence of spindle cells with cigar-shaped nuclei, interlacing fascicles, and a whorled pattern. "The involvement of many proteins, such as LHFPL3, SGK1, and RhoA, shown in the protein-protein interaction network, is well established in fibroid pathogenesis." (PMID 37686244, 2023). "Leiomyoma cells have higher levels of active RhoA than myometrial cells." (PMID 36430682, 2022).
lipomatosis (3 papers, 2015 to 2022). A neoplastic process characterized by diffuse overgrowth of mature adipose tissue. "In terms of adipogenic differentiation, miR-125a-3p and miR-483-5p promote adipogenesis by suppressing the RhoA/ROCK1/ERK1/2 pathway in multiple symmetric lipomatosis." (PMID 34060407, 2021). "For instance, when miR-125a-3p expression was up-regulated which then targeted RhoA leading to a down-regulation of RhoA/ROCK activity and followed by increased adipogenesis in subcutaneous WAT in patients with multiple symmetric lipomatosis." (PMID 35769086, 2022).
lung diseases (3 papers, 2021 to 2022). "This study is the first to document ARHGAP42 deficiency-associated lung disease and to implicate the RhoA/ROCK pathway as the potential underlying mechanism." (PMID 34232960, 2021). "Moreover, RhoA/ROCK activation has been reported to be associated with adult-type fibrotic lung diseases." (PMID 34232960, 2021). "Furthermore, miR-133a/RhoA axis has been reported to participate in the elevation of carbon dioxide in tissues in patients with severe lung diseases, including COPD." (PMID 36275894, 2022).
malignant glioma (3 papers, 2015 to 2022). A grade III or grade IV glioma arising from the central nervous system. "According to previous studies, RTN4A may inhibit the migration and invasion of human malignant glioma cells via the downregulation of RhoA-cofilin signalling." (PMID 35428758, 2022). "Furthermore, RHPN2 triggers the progression of malignant glioma via activation of RhoA, indicating that silencing of RHPN2 exerts an inhibitory impact on the development of malignancy." (PMID 31847864, 2019). "A recent study further demonstrated that RHPN2 could drive mesenchymal transformation in malignant glioma via triggering RhoA activation." (PMID 26647728, 2015).
mammary adenocarcinoma (3 papers, 2012 to 2015). "For example, one study found that the inhibition of RhoA induced the expansion of rat mammary adenocarcinoma cells in all directions with the subsequent appearance of round and flat cells due to Cdc24/Rac hyperactivity." (PMID 22550395, 2012). "EphA2 physically and functionally interacts with ErbB2 to amplify Ras/mitogen-activated protein kinase (MAPK) and RhoA signaling in tumor cells, indicating that EphA2 cooperates with ErbB2/Neu to promote mammary adenocarcinoma tumorigenesis and metastatic progression." (PMID 25013485, 2014).
memory impairment (3 papers, 2017 to 2022). "In this study, we show that TBI causes substantial motor, learning, and memory impairments in adult mice, which are alleviated by blocking RhoA-ROCK signaling via RhoA deletion from postnatal neurons or by treating mice with the ROCK inhibitor fasudil." (PMID 28878396, 2017). "Since phosphorylation of cofilin is an end target for RhoA pathways, we have analyzed p-cofilin levels as a neuronal plasticity marker, in mice showing memory impairments in the WRAM, well-performing mice and well-performing mice receiving proBDNF infusions in the hippocampus." (PMID 28912711, 2017).
myocardial ischemia (3 papers, 2019 to 2022). A disorder of cardiac function caused by insufficient blood flow to the muscle tissue of the heart. "More importantly, available report suggested that oxycodone ameliorated myocardial ischemia-reperfusion injury in rats via RhoA/ROCK1 signaling." (PMID 35170371, 2022). "Studies have shown the role of RhoA or RhoA effector molecule, Rho kinase (ROCK), in protecting the myocardium from reperfusion injury after myocardial ischemia, related to myocardial cell survival and Caspase-3 activation." (PMID 33763149, 2021).
oral squamous cell carcinoma (3 papers, 2019 to 2024). "Snail has recently been reported to inactivate RhoA at intercellular junctions to facilitate clustered cell migration in SAS oral squamous cell carcinoma cells." (PMID 38141763, 2024).
osteonecrosis (3 papers, 2022 to 2026). A none disease characterized by death of bone tissue due to a lack of blood supply. "It has also been demonstrated that miR-29 and miR-31-5p, which act on specific targets like RhoA and CALCR, promote osteonecrosis through programmed cell death." (PMID 38338876, 2024).
ovarian tumour (3 papers, 2019 to 2024). "Our findings provide advanced insights into the mode of action of the Ran-RhoA signalling axis and may represent a potential therapeutic avenue for drug development to prevent ovarian tumour metastasis." (PMID 31209254, 2019). "In renal and ovarian tumour models, it targets ZEB2 and RhoA and mediates TGF-beta-induced EMT." (PMID 38801504, 2024). "This could indicate that, while in other tumor types StarD13 is the main GAP for RhoA due to the absence of DLC1, in ovarian tumors DLC1 mainly drives this inhibition." (PMID 34958986, 2022).
pemphigus (3 papers, 2012 to 2023). Pemphigus is a group of rare autoimmune diseases that cause blistering of the skin and mucous membranes (mouth, nose, throat, eyes, and genitals).This conditioncan occur at any age, but often strikes people in middle or older age. "RhoA activity was furthermore linked to possible apoptotic signalling in pemphigus." (PMID 34434944, 2021). "Inhibition of Rac1 and RhoA by pemphigus autoantibodies targeting Dsg3 and Dsg1 showed disruption of cell–cell adhesion and blister formation in epidermis." (PMID 22796473, 2012). "Since inhibition of RhoA has been shown to be induced by pemphigus autoantibodies that disrupt Dsg3 and Dsg1 adhesion we also performed RhoA pull down in parallel using the GST fused Rhotekin-PBD." (PMID 22796473, 2012). "This was shown to reduce pemphigus IgG induced effects, indicating, that activation of RhoA in pemphigus might represent an insufficient rescue pathway." (PMID 34434944, 2021). "Previous work by others has found that activation of RhoA, a canonical upstream activator of MRTF and SRF, can prevent keratinocyte dissociation induced by pemphigus antibodies in vitro." (PMID 37471166, 2023).
preeclampsia (3 papers, 2014 to 2022). Preeclampsia is a hypertensive disorder of pregnancy that is characterized by new-onset hypertension with proteinuria presenting after 20 weeks of gestation, and depending on mild or severe forms may initially present with severe headache, visual disturbances, and hyperreflexia. "Increased blood pressure in preeclampsia is associated with marked vascular inflammation and ROS that may enhance vascular reactivity via the activation of RhoA/ROCK pathway." (PMID 29262624, 2017). "And knockdown of ROCK II exerted the similar effects with Fasudil, indicating that prevention of the development of preeclampsia by Fasudil is involved in RhoA signaling." (PMID 29262624, 2017). "Although expression of ROCK1 and ROCK2 was not different, a higher RhoA mRNA expression was found in placentae from women who suffered from preeclampsia compared with placentae from those that were normotensive." (PMID 25628539, 2014).
Priapism (3 papers, 2012 to 2024). A painful and harmful medical condition in which the erect penis doesn't return to its flaccid state, despite the absence of both physical and psychological stimulation, within four hours. "In priapism, deficient endothelial NO disrupts this feedback mechanism, downregulating RhoA/Rho-kinase activity." (PMID 39627696, 2024). "Mice deficient for the eNOS enzyme display reduced NO bioavailability associated with lower RhoA/Rho-kinase activity in the penis, as well as a priapism phenotype." (PMID 36176769, 2022). "Therefore, should impaired RhoA/ROCK-mediated vasoconstriction contribute to SCD-associated priapism, this pathway may become a novel therapeutic target in the management of this complication." (PMID 22745902, 2012). "Furthermore, men and mice with SCD show lower expression and activity of the RhoA-ROCK pathway, thus impairing the maintenance of the flaccid state of the penis and contributing to priapism." (PMID 36176769, 2022).
prostate tumors (3 papers, 2015 to 2024). "Interestingly, RhoA, which is an androgen receptor targeted gene, has also been shown to be dysregulated and overexpressed in AA prostate tumors." (PMID 38785827, 2024).
renal carcinoma (3 papers, 2011 to 2016). A carcinoma arising from the epithelium of the renal parenchyma or the renal pelvis. "Knockdown of prolyl-hydroxylases in HeLa cells resulted in activation of RhoA and RhoA had been shown to be induced by hypoxia in mouse embryonic fibroblasts and in renal cancer cells." (PMID 23418576, 2013). "Here, the authors show that in renal cancer cells, lysosphosphatidic acid does not utilize the RhoA pathway but specifically activates the Arf6 mesenchymal pathway via its GPCRs and EFA6 to promote invasion, metastasis and drug resistance." (PMID 26854204, 2016).